TMEM91 (transmembrane protein 91)
Synonyms: DSPC3; FLJ27310; IFITMD6; SynDIG3
Tractability: Antibody: UniProt predicts a signal peptide or a membrane-spanning region.
Safety:
Unwanted effects reported when the protein is acted on. In parentheses: how it was acted on, where the effect was seen, and who reports it.
aspirin-intolerant chronic urticaria (source: ClinPGx)
coronary artery disease (source: ClinPGx)
diarrhea (source: ClinPGx)
Gene: Protein-coding gene on chromosome 19 (41,350,911 to 41,384,083, forward strand). Ensembl gene ENSG00000142046.
Subcellular location: Membrane
Gene Ontology:
Cellular component: membrane
Genetic constraint (gnomAD): Loss-of-function variants: 7 observed, 15.36 expected, observed/expected ratio (o/e) 0.46, 90% interval 0.26 to 0.86. The upper end of that interval is the gene's LOEUF score, 0.86, which puts it in group 3 of 6, group 1 being the genes least tolerant of losing a copy. Missense variants: 193 observed, 238.15 expected, observed/expected ratio (o/e) 0.81, 90% interval 0.72 to 0.91. Synonymous variants: 87 observed, 105.72 expected, observed/expected ratio (o/e) 0.82, 90% interval 0.69 to 0.98.
Homologues: Orthologues: pig TMEM91 (82% identical), mouse Tmem91 (78% identical), chimpanzee TMEM91 (72% identical), guinea pig TMEM91 (56% identical), rat Tmem91 (55% identical), zebrafish tmem91 (31% identical). Paralogues in human: SYNDIG1 (38% identical), SYNDIG1L (38% identical), PMIS2 (15% identical).
Diseases named in the same sentence as TMEM91 in open-access papers:
TMEM91 is named in the same sentence as 4 diseases in open-access papers, as found by Europe PMC text mining. Sharing a sentence is not in itself a finding about the gene and the disease. The quoted sentences say what the papers report.
asthma (1 paper, 2020). "Among such loci identified by GWAS, chromosome 19q13 that carries genes, including TGFB1, B9D2 and TMEM91, has been reported to harbor multiple single-nucleotide polymorphisms (SNPs) that are linked to asthma, CF and/or COPD." (PMID 32500120, 2020).
colorectal cancer (1 paper, 2022). A primary or metastatic malignant neoplasm that affects the colon or rectum. "While the TMEM91 gene was the reported candidate gene for the colorectal cancer risk at the rs1800469, we find that the risk variant affected three proteins in either cis (B3GNT8 and TGFB1) or trans (B3GNT2)." (PMID 35079000, 2022).
Huntington disease (1 paper, 2020). Huntington disease (HD) is a rare neurodegenerative disorder of the central nervous system characterized by unwanted choreatic movements, behavioral and psychiatric disturbances and dementia. "Virtually nothing is known about the two vertebrate paralogues of SynDIG1, SynDIG1L and TMEM91, although SynDIG1L has been found downregulated in mouse models of Huntington's disease." (PMID 33108974, 2020).
migraine (1 paper, 2020). "The remaining three genes are located at two loci not previously identified for migraine (POC5 and ANKDD1B on chromosome 5q13.3, and TMEM91 on chromosome 19q13.2), thus, representing novel loci for migraine risks." (PMID 32121467, 2020).